TNF (tumor necrosis factor)
Diseases named in the same sentence as TNF in open-access papers (continued):
Sharing a sentence is not in itself a finding about the gene and the disease.
tumor (continued). "Upon stimulation by proinflammatory factors (LPS, TNF-α), TAMs activate into M1-like macrophages and kill tumor cells by producing reactive oxygen species and inflammatory cytokines (e.g. IL-6 and TNF-α)." (PMID 34178692, 2021). "On day 21, TNF-α neutralization after RFA treatment notably reduced lung metastasis compared with that in tumor-bearing mice and after RFA treatment alone." (PMID 34576115, 2021). "Maca was also shown to remodel the immunosuppressive tumor microenvironment into an immune-activated state with secretion of IL-12, TNF-alpha, and IFN-gamma." (PMID 34684284, 2021). "In the current study, tumor concentrations of TNF-alpha, IL-6, IL1-beta and MCP-1 were positively correlated with a higher OSCC volume." (PMID 33411841, 2021). "In the study, artemisinin was shown to significantly decrease TGF-β mRNA levels and populations of MDSCs and Treg cells within the tumor, while increasing TNF-α mRNA levels, CD4+ interferon gamma-expressed (IFN-γ+) T cells, and cytotoxic T lymphocytes." (PMID 34948368, 2021). "Multiple mechanisms mediate Mφ activation and their co-stimulation of T cells to promote anti-tumor immunity, mainly through tumor necrosis factor (TNF) superfamilies of receptors (Tnfrsf1a/b) and CD4024,25." (PMID 34103524, 2021). "In this study, we found an altered expression of adhesion molecules on endothelial cells and their ligands on tumor cells in the presence of TNF-α." (PMID 34222020, 2021). "In our study, tumor samples comprising C3 are rich in various anti-tumor cytokines, such as TNF and IFN-γ, and have abundant infiltration of immune cells including NKT cells and T lymphocytes as well as B lymphocytes." (PMID 33637086, 2021). "As a major cytokine in the tumor microenvironment, TNFα influences several of the hallmarks of cancer, such as stimulation of tumor growth, survival, invasion, metastasis, and angiogenesis." (PMID 34573003, 2021). "The studies focusing on local effects of TNF on tumour development revealed that constitutive TNF expression at the site of malignancy exerts strong and long-term suppression of tumour growth." (PMID 33446741, 2021). "Of note, the CD137+TNF-IFNγ- population represented 24% of the bulk tumor-specific reactive CD8+ TILs." (PMID 34707600, 2021). "Contrary to the anti-tumor effects of TNF, it is now clear that TNF-α is also involved in pathologic processes such as chronic inflammation, autoimmunity, and malignancy." (PMID 33920379, 2021). "Within the tumor milieu, the potent inflammatory cytokine TNFα has been the subject of intensive investigation." (PMID 34201054, 2021). "IL-10 inhibits tumor growth by hindering several inflammatory and angiogenic factors, including vascular endothelial growth factor, IL-1β, TNF-α, and IL-6." (PMID 34361836, 2021). "A notable exception was the HTCT-induced transcriptional upregulation of IFNɣ and of TNFα, the latter being a pleiotropic cytokine which is a key protagonist in immune homoeostasis, host defence and tumour surveillance." (PMID 33658617, 2021). "Because TNFα is manifested as a mild uncoupler of oxidative phosphorylation, the mitochondrial status of engineered tumor cells was monitored." (PMID 33957885, 2021). "TNF-α (tumor necrosis factor-α) was named after the discovery of its cytotoxicity to tumor cells in 1984; it plays a kind of antineoplastic cytokine in cytotoxicity for promoting tumor development and progression." (PMID 34375303, 2021). "During metastasis formation, ADAM17 is required to trigger necrotic cell death in endothelial cells via TNF in order to allow the extravasation of tumor-derived cells." (PMID 34831323, 2021). "Reduction of oxidative stress, by preventing TNFα-signaling in tumor cells or scavenging ROS with NAC, antagonizes the therapeutic effects of ACT." (PMID 33673398, 2021).
tumor (continued). "In cHL, TNF-α is mainly produced by H-RS, and it plays a significant role in the modulation of T-cell response by recruiting Th1 cells into the tumor microenvironment and regulating the production of other proinflammatory cytokines." (PMID 33684151, 2021). "The effects of TNF-α on tumor neovasculature and tumor interstitial fluid pressure that improve treatment efficacy are summarized." (PMID 33986746, 2021). "CD8+ cell secret cytotoxic molecules and cytokines, including perforin, granzyme, interferon-gamma, tumor necrosis factor-alpha and so on, which elicit anti-tumor effects." (PMID 34795362, 2021). "They found that this was maintained through the secretion of versican by tumor cells, which stimulated the production of TNFα by monocytes themselves in a TLR2-dependent manner." (PMID 34445397, 2021). "Consistently, Atg5 deficiency promotes the formation of effector memory CD8+ T cells, resulting in production of higher levels of IFNG and TNF/TNF‐α and enhanced tumor rejection." (PMID 34459017, 2021). "TNF is involved in the inflammation and cellular immune response as well as tumor regulatory mechanisms." (PMID 33851708, 2021). "Recent studies have even suggested that constitutive expression of TNF-α within the inflammatory tumor microenvironment plays a pro-tumorigenic role by enhancing cancer cell survival, angiogenesis, and metastasis formation." (PMID 33633307, 2021). "Within the tumor microenvironment, however, TNFα is one of the main mediators of cancer-related inflammation." (PMID 33540543, 2021). "Still, the anti-tumor effects of TNFα require greater concentrations than cells can physiologically produce within the tumor." (PMID 33498483, 2021). "Pro-inflammatory cytokines such as interleukin-1, interleukin-6, tumor necrosis factor α, are not only important impact factors for albumin production, but also critical in oncogenesis, angiogenesis and tumor progression." (PMID 33596518, 2021). "TNF is a pro-inflammatory cytokine predominantly produced by macrophages as well as tumor cells and initiates chronic inflammation." (PMID 34768966, 2021). "IL-6, IL-1β and TNF-α are secreted at high levels in and around the tumor environment after the exposure of MNPs, which alters the TME and improves immune response." (PMID 34834282, 2021). "The tumor necrosis factor can act as a tumor promoter, and it is highly involved in various carcinogenic functions, including metastasis and angiogenesis." (PMID 34439379, 2021). "Of the inflammatory cytokines mediating the crosstalk between tumor cells and immune cells, TNF appears to play a pivotal role." (PMID 34572737, 2021). "TNF-α has a direct killing effect on tumor cells, which plays a very crucial role in the host defense mechanism." (PMID 33490281, 2021). "Macrophage-derived TNF-α and IL-1β are strong inducers of IL-6 in tumor cells, a cytokine that in turn promotes intraosseous tumor growth, osteoclastogenesis, and osteolysis." (PMID 34064859, 2021). "Tissue damage occurring during tumor development and the release of alarm cytokines such as IL-1α, IL-1β, and TNFα induce the production of IL-6, IL-10, IL-11, and IL-23 by tissues and myeloid cells." (PMID 33498483, 2021). "Engagement of CD16 in response to mAb-coated tumor cells induces the secretion of TNF-α that mediate cell death of tumor cells expressing TNF-α receptor." (PMID 34359674, 2021). "More convincingly, authors neutralized TNF‐α in the serum of tumor‐bearing mice and observed retardation of blood influx together with a delay of bacterial tumor‐colonization." (PMID 33854892, 2021). "Now, it has been confirmed that tumor necrosis factor (TNF, formerly referred to as TNF-alpha) can favor tumor growth and/or progression in vitro and vivo experiments." (PMID 34888137, 2021). "And similar findings were obtained when we analyzed TNF‐α expression between tumor tissues and non‐tumor tissues." (PMID 34185422, 2021).
tumor (continued). "The measurement of the tumor volume demonstrated that MDA-MB-231 tumors grew in unstimulated mice, whereas tumor growth ceased in the TNF-α-treated mice." (PMID 34158609, 2021). "Tumour Necrosis Factor-a (TNF-a), a pro-inflammatory cytokine, plays an important role in inflammation, anti-tumor responses and homeostasis." (PMID 34837956, 2021). "To demonstrate that compound 1 can be exploited for delivering nanogold to αvβ3-positive tumors, we coated gold NPs with compound 1 and murine TNF, a cytokine endowed with potent anti-tumor activity." (PMID 34124009, 2021). "Inhibition of the TNFα/NFκB-driven proinflammatory signaling resulted in the suppression of tumor growth and progression in vivo and in vitro." (PMID 34603293, 2021). "Further, tumor-intrinsic NF-kB activity can be boosted by exogenous TNF treatment, leading to chemotherapy resistance." (PMID 34771644, 2021). "Studies have shown that beta-sitosterol can inhibit cell proliferation in transplanted tumours in mice by inhibiting the expression of IL-6, TNF and VEGF." (PMID 35069454, 2021). "Pro-inflammatory cytokines, such as interleukin-1 (IL-1), IL-6, IL-8, INF-γ, and TNF-α, favor tumor growth and invasion by promoting cell proliferation, epithelial-mesenchymal transition and angiogenesis, while increasing tumor immune surveillance." (PMID 34202728, 2021). "Catecholamines can promote macrophages to secrete pro-inflammatory factors such as IL-1β and TNF-α, intensifying the pro-tumor properties of macrophages." (PMID 34988010, 2021). "Tumor necrosis factor (TNF) is a cytokine that can kill tumor cells directly while exerting an antitumor effect by activating the immune system and leukocyte transendothelial migration." (PMID 34539886, 2021). "Conversely, MAIT cells can display an exhausted phenotype with reduced capacity to produce anti-tumour cytokines, such as IFNγ and TNFα." (PMID 33808058, 2021). "In a similar fashion, we noted an enrichment of TNF‐α+ macrophages in tumor homogenates, while the macrophage population expressing IL‐4R and CD206 were reduced." (PMID 33682324, 2021). "Blocking TNF and PD-1 increased the number and activity of tumor-infiltrating CD8+ TIL and enabled to achieve 75% survival versus 20% survival in the case of treatment with anti-PD-1 alone." (PMID 34367136, 2021). "While this is also still emerging, it appears that tumor-derived cytokines, including TGFβ and TNFα, impede pDC activation and IFNα biosynthesis." (PMID 34067257, 2021). "In the case of TNF-α, the results are also very contradictory because, in different cancers, it can have both apoptotic and survival impacts on tumor cells, and more studies are needed to find out the exact role of this cytokine." (PMID 34868907, 2021). "For instance, a recent study has shown miR-34a promoted the expression of B7-H3 and TNF-α in tumor microenvironment and negatively regulated T cell-mediated immune response, which thus induced immunosuppression and immune escape in CRC." (PMID 35111681, 2021). "Blockade of IL-6 signaling or TNF-α has already been shown to be effective in reducing tumor growth and metastasis in preclinical studies using PDAC mouse models as well as in the therapy of other tumor entities and inflammatory diseases." (PMID 34064969, 2021). "At the same time, TNF-α plays a biological role in tumor cells through the STAT3 signaling pathway, so the STAT3 signaling pathway is a bridge between inflammation and tumor." (PMID 33688358, 2021). "The most commonly used approach is intracellular cytokine staining (ICS) focusing on the detection of molecules such as interferon-gamma (IFNγ), tumor necrosis factor (TNF), and interleukin 2 (IL-2), after recognition of tumor-antigens." (PMID 34707600, 2021). "Inflammatory cytokines (notably interleukins IL-1, IL-6, and TNFα) released from tumor cells induce CRP protein production in hepatocytes." (PMID 34830745, 2021).
tumor (continued). "Preclinical studies have shown that the anti-tumor effect of TNF is due to the destruction of tumor vascular system." (PMID 34079469, 2021). "NK cell invasion and retention in tumor tissue was low despite a high local level of chemokines, such as IL-8, and increased levels of IFN-γ and TNF-α in comparison to the mucosa adjacent to the tumor tissue." (PMID 34925361, 2021). "Resident cells (macrophages and dendritic cells) react to tumor antigens and initiate inflammation by secreting proinflammatory mediators, such as cytokines (IL-1β, IL-6, TNF-α)." (PMID 35116038, 2021). "We analyzed the mRNA expression profiles of metastatic brain tissues and TNF-α treated cancer cells to understand the changes in adhesion molecule expression during the tumor phase." (PMID 34222020, 2021). "Higher tumor levels of TNF-alpha, IL-6, IL1-beta and MCP-1 were positively correlated with OSCC growth." (PMID 33411841, 2021). "CD8 TRM cells are primed to secrete large quantities of IFNγ and TNFα following antigen re-exposure in the context of both viral and tumor responses as well as models of autoimmune vitiligo." (PMID 34362825, 2021). "Among proinflammatory cytokines, TNF-α has a multifunctional role in regulating processes such as coagulation, metabolism, apoptosis, inflammation, and tumor growth or invasion, along with vascular functions." (PMID 34764420, 2021). "TNF-alpha levels were about 4-fold higher in the tumor microenvironment from stressed rats (isolated, 7.531 ± 3.099 pg/μg vs grouped, 1.787 ± 0.3129 pg/μg) (p = 0.0034)." (PMID 33411841, 2021). "As a stimulatory cytokine, TNFα contributes to the antitumor activity of cytotoxic T cells by inducing proliferative arrest and/or apoptosis, and further enhances tumor cytotoxicity threshold to T cell-derived TNF." (PMID 34603277, 2021). "Similar to IL-6 and TNF-α, TGF-β is associated with a wide range of tumor-inductive or cancer-supportive mechanisms, such as EMT, immune escape, the formation of blood vessels, as well as the suppression of apoptotic pathways." (PMID 33429846, 2021). "CD8+ T cells produce IFN-γ, TNF and granzyme B by binding T cell receptors to target tumor cells, leading to tumor cell clearance." (PMID 34305884, 2021). "Our protocol concurrently detecting intracellular CD137, TNF, and IFNγ by flow cytometry identified the majority of the presumed tumor-specific reactive TIL repertoire in the TME." (PMID 34707600, 2021). "The nude mouse xenograft tumor model was used to further validate the KRAS mutation-dependent PDAC tumor growth promoted by IL-1β, TNF-α, and Shh stimulation." (PMID 34046348, 2021). "In fact, compared to PBS-treated tumours, cGAMP-treated tumours showed 3.9-fold and 2.2-fold increases of TNFα and IFNγ, respectively." (PMID 34285232, 2021). "TAMs sense hypoxia in avascular areas of tumors and react in turn by releasing pro-angiogenic factors such as FGF-2, TNF-α, and VEGFs, which again promotes tumor oxygenation by the direct recruitment of endothelial cells." (PMID 33747916, 2021). "This anti-CCL1 CAR T cell showed the in vitro and in vivo strong functionality against CLL1+ tumor cells with a wide production of effector cytokines and chemokines including GM-CSF, TNF-α, IFN-γ, and IL-13." (PMID 34412685, 2021). "Though it is mainly produced by macrophages, other cells (such as fibroblasts, neutrophils, smooth muscle cells, and neoplasm cells) can also be a source of TNF-α." (PMID 34573967, 2021). "In a mouse MC38 tumor model, Iida reported that depletion of the gut microbiota significantly reduced TNF activation and weakened the antitumor effects of ODN and anti-IL-10R." (PMID 35096962, 2021). "The first signal controls IMCs production, mainly mediated by tumor-derived growth factors, such as IL-6, IL-11, IL-17A, G-CSF, GM-CSF, TNFα, and involves signal pathways including STAT3, IRF8, C/EBPβ, RB1, Notch, adenosine receptors A2b, NLRP3, and others." (PMID 34680276, 2021).
tumor (continued). "For example, platelet-derived growth factor (PDGF), epidermal growth factor (EGF), tumor necrosis factor α (TNFα), interleukin-1 (IL-1), transforming growth factor β (TGFβ), etc. can stimulate ROS production and promote tumor progression." (PMID 33673398, 2021). "When produced from these adenoviruses, IL-2 and TNFα can recruit NK and T lymphocytes into the tumor bed." (PMID 33540543, 2021). "Inhibition of PGE2 production by indomethacin, a potent inhibitor of cyclooxygenase (COX) enzymes, induces the expression of tumor necrosis factor (Tnf) mRNA in the necrotic tumor cell supernatants." (PMID 33875721, 2021). "This article reviews the two sides of the interaction between TGF-β and TNF-α during tumor formation." (PMID 35069596, 2021). "A large amount of TNF-α was detected in the control group, and the deeper the tumor, the higher the density of TNF-α." (PMID 34069607, 2021). "M1 macrophages can exert their anti-tumor and immune-enhancing effects by secreting inflammatory factors, chemokines, effector molecules, and TNF- molecules." (PMID 34631695, 2021). "When vaccinated with P2Et-pretreated 4T1 cells, the primary tumor growth was improved by yielding IL-2, TNFα, IL-4, IL-5, and IFNγ-producing CD4+ and CD8+ T lymphocytes." (PMID 34948368, 2021). "A profound release of cytokines, such as IFN-γ and TNF-α, by NK cells can boost the overall anti-tumor response by stimulating antigen presentation, Th1 polarization, and CD8 effector functions." (PMID 34203549, 2021). "TNFRSF1B, a receptor of TNF and lymphotoxia-α, can directly promote tumor cell proliferation and activate immunosuppressive cells." (PMID 34880206, 2021). "Remarkably, recombinant human TNF-α has been shown to increase the quantity of TNFR2 expressed at the surface for a number of tumor epithelial-like cell lines." (PMID 34712661, 2021). "In this phase, N1 TANs exert cytolytic functions primarily through ROS production and stimulate tumor specific T cells by antigen presentation and pro-inflammatory cytokine production such as IL-1β, IL-6, TNF-α, or IL-17A." (PMID 34168563, 2021). "It has been reported that TNF‐α or IL‐6 promotes tumour proliferation and invasion in an autocrine‐dependent manner." (PMID 33410581, 2021). "Pre-operatively, circulating neutrophil counts were found to correlate with increased tumor burden, as well as with increased levels of the neutrophil-mobilizing cytokines, interleukin (IL)-1β, IL-17A and tumor necrosis factor-α (TNF-α)." (PMID 34168563, 2021). "M1-like macrophages induced apoptosis and cell cycle arrest of tumor cells by releasing multiple factors including TNF-α, IL-6 and ROS." (PMID 34400883, 2021). "DOX administration in tumor-bearing mice significantly ameliorated the tumor-induced upregulation of IL-1β, IL-6, TNF-α, and Mcp-1." (PMID 34445729, 2021). "We further explored the expression of cytotoxic factors, including interferon γ (IFN-γ), tumor necrosis factor α (TNF-α) and granzyme B, in the tumor-infiltrating T cells." (PMID 34373258, 2021). "TNF-α mediated matrix metalloproteinase (MMP) production in tumor cells or the TME also promotes tumor expansion." (PMID 33986746, 2021). "MDSCs are actively drawn and activated in the tumors by various secretory products like PGE2, VEGF, GM-CSF, IL-6, TNF-α, IL-10, and IL-1β elaborated by TIICs, CAFs, and the tumor cells themselves." (PMID 33996630, 2021). "The pro-inflammatory cytokine TNF-α has been associated with the acquisition of both EMT and CSC characteristics in various tumor entities, including PDAC." (PMID 34064969, 2021). "APS-activated macrophages, which increase the concentration of nitric oxide (NO) and TNF-α, acting as an upstream inhibitor of tumor cell proliferation with G1 cycle blockage and modulating genes associated with apoptosis, prevent cancer cells growth." (PMID 34721026, 2021). "These seemingly paradoxical observations can be attributed to the TNF-α axis acting a dual function in tumor progression." (PMID 33461943, 2021).